ULK4 (unc-51 like kinase 4)
Diseases named in the same sentence as ULK4 in open-access papers (continued):
Sharing a sentence is not in itself a finding about the gene and the disease.
Obesity (2 papers, 2022 to 2024). Accumulation of substantial excess body fat. "Our work identified vascular dysfunction risk genes, including Sox17, Ulk4, Nbeal1, Cdkn1a and Plec, as obesity-regulated genes in the endothelium." (PMID 36400935, 2022). "Several potential functional genes, including CHAF1A, CEP192, ULK4, CYP2D6, AS3MT, and WARS2, were identified as common genetic factors linking obesity and IS." (PMID 39734234, 2024). "The identification of CHAF1A, CEP192, ULK4, CYP2D6, AS3MT, and WARS2 as potential functional genes common to both obesity and IS enriched our understanding of their genetic interplay, potentially advanced our grasp of their pathogenesis and therapeutic targets." (PMID 39734234, 2024).
primary biliary cholangitis (2 papers, 2021 to 2022). Primary biliary cholangitis (PBC) is a chronic and slowly progressive cholestatic liver disease of autoimmune etiology characterized by injury of the intrahepatic bile ducts that may eventually lead to liver failure. "Furthermore, ULK4 has been associated with primary biliary cholangitis (PBC); expression levels of ULK4 were found to be significantly higher in PBC patients than in healthy controls, suggesting a potential relationship between ULK4 and inflammation." (PMID 35630356, 2022).
small vessel stroke (2 papers, 2019 to 2021). "Locus 3p22.1 [ULK4] of DL-IS risk seems likely to be associated with ULK4; recently, ULK4 was identified by GWAS and brain eQTL to be a susceptibility gene for IS and small vessel stroke in trans-ethnic datasets." (PMID 33632238, 2021). "ULK4 is a susceptibility gene for ischemic stroke and small vessel stroke." (PMID 32038707, 2019).
anxiety disorder (1 paper, 2018). A category of psychiatric disorders which are characterized by anxious feelings or fear often accompanied by physical symptoms associated with anxiety. "Considering significant decreases in Gad67 neurons in the hippocampus and basolateral amygdala of Ulk4+/tm1a mice, and the correlating functions of GAD1 in humans, it will be interesting to investigate if polymorphisms of the ULK4 link to anxiety disorders in patients." (PMID 29391390, 2018).
chordoma (1 paper, 2017). Chordomas are rare malignant tumors arising from embryonic remnants of the notochord in axial skeleton. "Although little is known about ULK4 function, its role in chordoma deserves further investigation since the other members of the family have been implicated in autophagic pathways." (PMID 28835717, 2017). "ULK4, NPR1 and CDKL4 were the top most expressed kinases in the Chor-IN-1 cell line, while FGFR3, KDR and WNK2 were less expressed or absent in Chor-IN-1 cells as compared to the other chordoma lines." (PMID 28835717, 2017).
diffuse gastric adenocarcinoma (1 paper, 2021). An adenocarcinoma arising from the stomach. "Four DEGs including ATG10, ATG16L2, ULK4 and GABARAPL1 showed differences in diffuse gastric adenocarcinoma subgroup, while other four DEGs including ATG7 (probe 224025_s_at), GABARAPL1, WIPI2 and GABARAPL3 showed differences in gastric intestinal type adenocarcinoma subgroup." (PMID 33604190, 2021).
holoprosencephaly (1 paper, 2023). Holoprosencephaly (HPE) is a complex brain malformation resulting from incomplete cleavage of the prosencephalon, occurring between the 18th and 28th day of gestation, and affecting both the forebrain and face, which results in neurological manifestations and facial anomalies of variable severity. "A recent study identified Ulk4 as a genetic modifier of the holoprosencephaly phenotype caused by impaired Shh pathway activity." (PMID 38096226, 2023). "The positive role of Ulk4 in Shh signaling could explain why elevated expression of Ulk4 in certain genetic background could suppress the heart outflow tract defects and holoprosencephaly caused by partially reduced Shh signaling activity in LRP2-deficient mice." (PMID 38096226, 2023).
neuroblastoma (1 paper, 2021). Neuroblastoma (NB) is the most common solid, extracranial childhood tumor. "Deletion of Ulk4 in human neuroblastoma cells disrupted the composition of microtubules, which led to compromised neuritogenesis and cell motility." (PMID 34235142, 2021). "Previously, we have shown that Ulk4 depletion inhibits cell cycle progression in cultured human neuroblastoma cell line (SH-5YSY) and Ulk4-knockdown brains." (PMID 34235142, 2021).
promyelocytic leukemia (1 paper, 2025). "To determine whether SUMOylation and SIM mediates Ulk4 condensation as is the case for promyelocytic leukemia (PLM) bodies, we co-expressed Stk36-EE with wild-type (Ulk4-WT), SUMOylation deficient (Ulk4-K1030R) or SIM-mutated Ulk4 (Ulk4-ΔSIM) in HEK293T cells." (PMID 40171800, 2025).
psychiatric disorder (6 papers, 2016 to 2024). A disorder characterized by behavioral and/or psychological abnormalities, often accompanied by physical symptoms. "Notably, the spatiotemporal expression pattern of Ift172 is similar to that of Ulk4, a rare risk factor we uncovered recently which is implicated in neocortical development and mental illness." (PMID 31850339, 2019).
cancer (3 papers, 2015 to 2021). A tumor composed of atypical neoplastic, often pleomorphic cells that invade other tissues. "Predicted HFI SNVs were not distributed evenly across disease subsets; SNVs in ULK4, BMP2K, PALB2, ALPK3 were more frequent in triple negative cancers (TNBC) whereas SNVs in EPHA2 was more common in ER positive cancers." (PMID 26420498, 2015).
neurodevelopmental disorder (3 papers, 2016 to 2021). A behavioral and cognitive disorder with onset during the developmental period that involves impaired or aberrant development of intellectual, motor, or social functions. "Our results and those of others strongly indicate that Ulk4 closely orchestrates brain development, which potentially connects Ulk4 deficiency with neurodevelopmental disorders." (PMID 34235142, 2021). "Deletion of Ulk4 selectively disrupts the cellular architecture of layers II–III, and V in the cerebral cortex, which may predispose the occurrence of many neurodevelopmental disorders." (PMID 34235142, 2021). "In contrast to previous reports, our Ulk4 mice presented significantly thinner layers of II–III, and V, the most vulnerable regions for a range of neurodevelopmental disorders including SCZ." (PMID 34235142, 2021).
infection (2 papers, 2021 to 2024). The state of being infected such as from the introduction of a foreign agent such as serum, vaccine, antigenic substance or organism. "Next, we expressed human Ulk4-WT, Ulk4-KR, or Ulk4-ΔSIM via lentiviral infection in NIH3T3 cells with endogenous Ulk4 depleted by shRNA and treated the cells with or without Shh." (PMID 39605492, 2024).
ULK4 also shares sentences with these, for which no sentence is quoted: breast carcinoma (2 papers); depression (2); myocardial infarction (2); type B aortic dissection (2); autistic spectrum disorder (1); behavioral disorder (1); blood pressure (1); cardiovascular disease (1); childhood asthma (1); Cohen syndrome (1); coronary artery disease (1); developmental delay (1); fibrosis (1); gastric cancer (1); gastric intestinal type adenocarcinoma (1); glioma (1); heart disorder (1); Intellectual disability (1); ischemic stroke (1); Macrocephaly (1); monoclonal gammopathy (1); neurologic disease (1); nicotine dependence (1); Pigmentary retinopathy (1); psoriasis (1); psychosis (1); pulmonary disease (1); renal carcinoma (1); Truncal obesity (1); type 2 diabetes (1).